C1orf146 (chromosome 1 open reading frame 146)
Description:
Plays a key role in reinforcing the integrity of the central element of the synaptonemal complex (SC) thereby stabilizing SC, ensuring progression of meiotic prophase I in male and female germ cells (By similarity). Promotes homologous recombination and crossing-over in meiotic prophase I via its association with SHOC1 (By similarity). Required for the localization of TEX11 and MSH4 to recombination intermediates (By similarity).
Synonyms: SPO16; SCRE
Tractability: No criterion of Open Targets' tractability assessment is met for any kind of drug.
Gene: Protein-coding gene on chromosome 1 (92,217,915 to 92,245,813, forward strand). Ensembl gene ENSG00000203910.
Subcellular location: Chromosome
Subcellular location (Human Protein Atlas): Centriolar satellite
Gene Ontology:
Biological process: homologous chromosome pairing at meiosis; meiotic DNA double-strand break formation; reciprocal meiotic recombination; resolution of meiotic recombination intermediates; spermatogenesis; synaptonemal complex assembly
Cellular component: chromosome; recombination nodule
Genetic constraint (gnomAD): Loss-of-function variants: 2 observed, 2.28 expected, observed/expected ratio (o/e) 0.88, 90% interval 0.33 to 1.85. That is too few expected variants to judge how well the gene tolerates losing a copy. Missense variants: 33 observed, 33.5 expected, observed/expected ratio (o/e) 0.99, 90% interval 0.75 to 1.32. Synonymous variants: 8 observed, 11.07 expected, observed/expected ratio (o/e) 0.72, 90% interval 0.42 to 1.3.
Homologues: Orthologues: chimpanzee C1H1orf146 (100% identical), dog C1orf146 (87% identical), rabbit C1orf146 (86% identical), pig C1orf146 (83% identical), mouse 1700028K03Rik (82% identical), guinea pig C1orf146 (69% identical), tropical clawed frog c4h1orf146 (50% identical).
Diseases named in the same sentence as C1orf146 in open-access papers:
C1orf146 is named in the same sentence as 5 diseases in open-access papers, as found by Europe PMC text mining. Sharing a sentence is not in itself a finding about the gene and the disease. The quoted sentences say what the papers report.
female infertility (1 paper, 2025). Diminished or absent ability of a female to achieve conception. "Although it is not known whether the remaining genes may lead to female infertility, it is noteworthy that in seven of them (ADAD2, AR, C1orf146, MLH3, RAD21L1, SYCP3, and TERB1), the corresponding female KO mice are infertile." (PMID 40896145, 2025).
C1orf146 also shares sentences with these, for which no sentence is quoted: acute kidney injury (1 paper); chronic kidney disease (1); hyperphosphatemia (1); infertile (1).